ATG5 (autophagy related 5)
Diseases named in the same sentence as ATG5 in open-access papers (continued):
Sharing a sentence is not in itself a finding about the gene and the disease.
pancreatic cancer (continued). "AZD has also been shown to inhibits pancreatic cancer growth and metastasis through ROS-mediated apoptosis, and also induces autophagy and apoptosis via AKT/mTOR/Atg5 pathways." (PMID 34944759, 2021). "For example, silencing of ATG5 or ATG7 in GEM models of KRASG12D- or BRAFV600E-driven cancer significantly delayed the onset and altered the histopathology of lung or pancreatic cancer." (PMID 34298710, 2021). "Recently, it was reported that silencing receptor for advanced glycation end products (RAGE) or Atg5 using shRNA significantly inhibited IL-6 induced autophagy and mitochondrial STAT3 activation in pancreatic cancer cells." (PMID 24796733, 2014). "Mechanistically, we found that THM mediated the post-transcriptional regulation of autophagy activation by targeting YTHDF2, thereby preventing the reading of the m6A modifications of ATG5 and ATG7 mRNAs, ultimately resulting in autophagic death in pancreatic cancer cells." (PMID 40756353, 2025). "Moreover, depletion of NT5E, ATG5, FOXP3, and IFNG inhibited the colony formation ability of pancreatic cancer cell." (PMID 38395786, 2024). "Studies in Kras-mutant pancreatic cancer mice have shown that the absence of autophagy genes such as ATG5 or ATG7 blocks the progression from low- to high-grade pancreatic intraepithelial neoplasia and pancreatic ductal adenocarcinoma." (PMID 38987818, 2024). "Like the knockdown of autophagy-related 5 (ATG5) or ATG7, the knockdown of NCOA4 also blocks ferritin degradation and suppresses erastin-induced ferroptosis in fibroblasts and pancreatic cancer cells, whereas the overexpression of NCOA4 promotes ferroptosis by degrading ferritin." (PMID 33117818, 2020). "Since ATG5 and Beclin 1 are both known to be direct targets of miR-30a, we hypothesized that YY1 and miR-30a might form a functional regulatory circuit that modulates autophagy in pancreatic cancer cells." (PMID 29052509, 2017).
osteosarcoma (32 papers, 2013 to 2025). A usually aggressive malignant bone-forming mesenchymal neoplasm, predominantly affecting adolescents and young adults. "We demonstrated that TSSC3 was an independent prognostic marker for overall survival in osteosarcoma, and positive ATG5 expression associated with positive TSSC3 expression suggested a favorable prognosis for patients." (PMID 30092789, 2018). "In the present study, we demonstrated that TSSC3 expression associated with ATG5 expression might be a favorable prognostic marker of osteosarcoma." (PMID 30092789, 2018). "We also revealed that TSSC3-associated positive ATG5 expression might be a potential predictor of favorable prognosis in patients with osteosarcoma." (PMID 30092789, 2018). "Exosomal lncRNA OIP5-AS1 promotes osteosarcoma progression by regulating angiogenesis and autophagy via the miR-153/autophagy-related 5 (ATG5 axis)." (PMID 40002766, 2025). "Anlotinib inhibited the migration and invasion of osteosarcoma cells but promoted autophagy and increased ATG5 expression." (PMID 38381883, 2024). "The importance of VPS37A UEVL in autophagy was further verified using VPS37A KO U-2 OS human osteosarcoma cells in which the level of HT-GFP processing during autophagy was also found to be comparable to that in LC3 conjugation-defective ATG5 KO cells." (PMID 39607828, 2024). "Y-27632 decreased the migration and invasion of osteosarcoma cells, while these effects were reversed by ATG5 overexpression." (PMID 38381883, 2024). "To confirm the role of anlotinib-induced autophagy in osteosarcoma cell metastasis, we knocked down ATG5 with short hairpin RNA (shRNA) to inhibit autophagy." (PMID 38381883, 2024). "Taken together, these data indicated that anlotinib treatment induced ATG5-dependent autophagy and that inhibition of autophagy enhanced the inhibitory effects of anlotinib on osteosarcoma metastasis through EMT and the RhoA-ROCK-LIMK2 pathway." (PMID 38381883, 2024). "In contrast, inducing autophagy via ATG5 overexpression in osteosarcoma cells increased their invasion and migration abilities." (PMID 38381883, 2024). "DICER1‐AS1 was shown to be an oncogenic factor in osteosarcoma that promotes osteosarcoma cell progression by regulating the miR‐30b/ATG5 pathway." (PMID 36708020, 2023). "As TGF-β is also known to exert pro-angiogenic properties in osteosarcoma, we next analysed the presence of endothelial cells within the WT or Atg5 KO tumors." (PMID 40396018, 2022). "In osteosarcoma cells, autophagy protein 5 (ATG5) not only participates in the formation of autophagosomes but also promotes cancer cell proliferation and invasion." (PMID 35291564, 2022). "The activation of Atg5/Atg7-dependent pathways through the upregulation of LC3B-II, Atg5, and Atg7 levels was observed in honokiol-treated osteosarcoma HOS and U2OS cells and leads to the accumulation of autophagic vacuoles." (PMID 31877856, 2019). "Taken together, these results showed that TSSC3 is an independent prognostic marker for OS and positive expression of both TSSC3 and ATG5 is a potential predictor of favorable prognosis in osteosarcoma." (PMID 30092789, 2018). "We then used IHC staining of above tissues to investigate the correlations between TSSC3, ATG5, and P62 expression and clinicopathological features of osteosarcoma." (PMID 30092789, 2018). "We found that ATG5 expression correlated positively with TSSC3 expression in human osteosarcoma tissues." (PMID 30092789, 2018). "DICER1-AS1 has been shown to enhance proliferation, invasion and autophagy through the miR-30b/ATG5 axis in osteosarcoma cells." (PMID 30619763, 2018). "We investigated the dynamic expression patterns of TSSC3 and autophagy-related proteins (autophagy related 5 (ATG5) and P62) in 33 human benign bone tumors and 58 osteosarcoma tissues using immunohistochemistry." (PMID 30092789, 2018). "Overall, these data suggested that ATG5 expression positively correlated with TSSC3 expression in osteosarcoma tissues." (PMID 30092789, 2018).
osteosarcoma (continued). "We found ATG5 expression is positively correlated with TSSC3 expression in osteosarcoma samples, and the relationship between TSSC3 and autophagy had never been reported before." (PMID 30092789, 2018). "In the present study, we investigated the correlation between TSSC3 and autophagy-related gene 5 (ATG5) protein expression (one of the key proteins for the formation of autophagosomes) in human osteosarcoma tissues and their prognostic value in osteosarcoma." (PMID 30092789, 2018). "In the present study, we found that ATG5 was significantly downregulated, together with an accumulation of P62 in osteosarcoma tissues." (PMID 30092789, 2018). "On the contrary, knockdown of ATG5 in osteosarcoma cells has an opposing effect on camptothecin-induced cytotoxicity." (PMID 29382381, 2018). "To examine the correlation between TSSC3 and autophagy, we first applied immunohistochemical staining to examine the TSSC3, ATG5, and P62 expression in human benign bone and soft tissue tumors, and osteosarcoma." (PMID 30092789, 2018). "Anlotinib-induced autophagy promoted migration and invasion by activating EMT and cytoskeletal rearrangement through ATG5 both in vitro and in vivo, and inhibition of anlotinib-induced autophagy enhanced the inhibitory effects of anlotinib on osteosarcoma metastasis." (PMID 38381883, 2024). "Furthermore, these effects were enhanced by ATG5 depletion, which resulted in reduced metastasis of osteosarcoma cells." (PMID 38381883, 2024). "ATG5 knockdown reduces chemotherapy-induced oxidative stress in osteosarcoma cells." (PMID 39931517, 2024). "ATG5 overexpression promoted EMT as well as osteosarcoma cell migration." (PMID 38381883, 2024). "Interestingly, as shown in the results, inhibition of anlotinib-induced autophagy by ATG5 knockdown further enhanced the inhibitory effect of anlotinib on the invasion and migration of osteosarcoma cells." (PMID 38381883, 2024). "Furthermore, to validate the effect of anlotinib-induced autophagy on osteosarcoma cell metastasis, an ATG5 overexpression vector was transfected into KHOS cells." (PMID 38381883, 2024). "Research has found that ATG5 silencing could abolish the EMT promotion by miR-210-5p in osteosarcoma." (PMID 34901004, 2021). "Knockdown of lncRNA DICER1-AS1 inhibits ATG5 protein levels in human osteosarcoma cells." (PMID 32377431, 2020). "Additionally, knockdown of autophagy protein 5 (ATG5) was shown to reduce chemotherapy-induced oxidative stress in osteosarcoma cells." (PMID 32210013, 2020). "Thus, many discrepancies remain, and there are few studies on the expression dynamics of ATG5 and P62 and their prognostic roles in osteosarcoma." (PMID 30092789, 2018). "Interestingly, a higher IHC score for ATG5 was found in osteosarcoma patients with positive expression of TSSC3." (PMID 30092789, 2018). "Surprisingly, neither the expression of ATG5 nor P62 seemed to be associated with the clinicopathological features of osteosarcoma." (PMID 30092789, 2018). "In addition, significantly higher conversion levels of LC3-I to LC3-II and high expression levels of Atg5 were also confirmed in the osteosarcoma cells transfected with miR-155 mimics (P<0.01 and P<0.05 respectively)." (PMID 25009614, 2014). "In addition, immunoblot analysis revealed significantly higher conversion levels of LC3-I to LC3-II and a higher level of Atg5 expression in the osteosarcoma cells that had been treated with 0.2 μg/ml Dox or 20 μM Cis." (PMID 25009614, 2014). "Furthermore, he suggests that the presence of TSSC3 in conjunction with ATG5 expression could potentially act as a promising prognostic marker for osteosarcoma patients." (PMID 39655055, 2024). "However, loss of Atg5 in a non-responsive, poorly ciliated 45Ca osteosarcoma cell line does not result in changes to cilia frequency or Gli1 mRNA." (PMID 37845394, 2023).
osteosarcoma (continued). "In addition, TSSC3 is an independent prognostic marker for OS in patients with osteosarcoma, and TSSC3-associated positive ATG5 expression might be a potential applicable predictor of favorable prognosis." (PMID 30092789, 2018). "Thus, we inferred that positive ATG5 expression in patients with TSSC3(+) osteosarcoma might suggest a favorable prognosis." (PMID 30092789, 2018). "Thus, positive ATG5 expression could be a potential predictor of favorable prognosis in patients with TSSC3(+) osteosarcoma." (PMID 30092789, 2018). "In osteosarcoma, Spautin-1–mediated inhibition of USP13 degrades METTL3, destabilizing ATG5 mRNA and impairing autophagy and glycolysis, which ultimately suppresses tumor growth." (PMID 40370434, 2025). "Studies have reported elevated expression of the autophagy-related proteins Atg-5, Beclin 1, and LC3-II, along with increased autophagic flux in Neuro-2a and human osteosarcoma cell lines, respectively." (PMID 38267572, 2024). "Moreover, the osteosarcoma-derived exosome that enriched the lncRNA OIP5-AS1 regulates osteosarcoma tumor angiogenesis through miR-153 and ATG5." (PMID 37377390, 2023). "In addition, some potential downstream genes of miR-30b-3p, such as ATG5, PAK1, FOXP4, and MYO10 also exerted crucial roles in osteosarcoma." (PMID 35123530, 2022). "In addition, overexpression of TSSC3 in osteosarcoma cell lines increased BECN1 and ATG5 mRNA levels." (PMID 30092789, 2018). "Importantly, we demonstrated that ATG5 expression was closely and positively correlated with TSSC3 expression in osteosarcoma for the first time, indicating there was a potential correlation between TSSC3 and autophagy." (PMID 30092789, 2018). "In human osteosarcoma U2OS cells, ISO also induced GFP-LC3 puncta but failed to do so upon knockout of the essential autophagy gene ATG5, indicating that the formation of GFP-LC3 puncta is indeed coupled to autophagy." (PMID 33243998, 2020).
systemic lupus erythematosus (30 papers, 2012 to 2024). An autoimmune multi-organ disease typically associated with vasculopathy and autoantibody production. "Previous studies have revealed that ATG5 polymorphisms are linked to a wide range of immune-mediated and autoimmune diseases, including multiple sclerosis, systemic lupus erythematosus, and rheumatoid arthritis." (PMID 35518570, 2022). "Autophagy genes, such as ATG5, has been reported to be associated with an increased risk of developing lupus." (PMID 34335611, 2021). "Consistent with this notion, LAP deficiency in mice includes the establishment of lupus-like autoimmune disease, a syndrome that has been linked to Atg5 gene mutations in humans." (PMID 34363750, 2021). "Intron SNPs in the ATG5 gene (rs573775 and rs665791) and the SNPs in the PRDM1-ATG5 intergenic region (rs548234 and rs6937876) confer to the susceptibility of developing systemic lupus erythematosus in different populations." (PMID 32377431, 2020). "Several GWASs for systemic lupus erythematosus (SLE) confirmed genetic associations between common variants in/near ATG5 and SLE, in Caucasians and Asians." (PMID 30386331, 2018). "Epidemiological studies in Caucasian and Chinese populations demonstrated a positive association between Atg5 expression and systemic lupus erythematosus (SLE) by meta-analysis." (PMID 28895911, 2017). "Genome-wide association studies have shown association between single nucleotide polymorphisms (SNPs) in autophagy related gene 5 (Atg5), and Atg16l1 with susceptibility to systemic lupus erythematosus (SLE) and Crohn’s disease, respectively." (PMID 23596443, 2013). "For instance, several SNPs in the Atg5 gene give susceptibility to lupus." (PMID 33187196, 2020). "Moreover, polymorphisms in IRGM and ATG5 polymorphisms, and variations in PRDM1-ATG5 intergenic region have been associated with systemic lupus erythematosus (SLE)." (PMID 30127786, 2018). "In addition, GWAS in lupus cohorts have identified that several SNPs in the Atg5 gene confer genetic susceptibility to lupus." (PMID 30108582, 2018). "In addition, in a follow-up study, a SNP in the Atg5 gene, rs573775, was identified to be related to IL-10 production and higher risk of lupus." (PMID 30108582, 2018). "For instance, in chronic autoimmune skin diseases, psoriasis has been reported that could be associated with SNPs in the ATG16L1 gene, and systemic lupus erythematosus (SLE) could be associated with a genetic variant within or near ATG5 gene." (PMID 27941683, 2016). "It is of interest that genomewide association studies (GWAS) have linked several single nucleotide polymorphisms (SNPs) in ATG5, an autophagy protein, to systemic lupus erythematosus (SLE) susceptibility." (PMID 21994884, 2012). "Deletion of Atg5 via CD21-Cre or CD19-Cre causes a notable reduction in autoantibody production and kidney inflammation in genetic mouse models of systemic lupus erythematosus (SLE)." (PMID 39139569, 2024). "While it is known that both common and rare variants of ATG5 are associated with SLE susceptibility, the precise mechanism by which ATG5 contributes to lupus is not yet fully understood." (PMID 37504294, 2023). "Other researches have also found some correlation of ATG5 gene variants with SLE in Caucasian population and significant positive correlations of ATG5 expression with systemic lupus erythematosus in Chinese Han population." (PMID 35518570, 2022). "B cell-specific deletion of Atg5 in lupus-prone mice demonstrated that B cell autophagy is vital for maintaining autoreactive B cells." (PMID 32462028, 2020). "To further understand the role of autophagy in lupus, we used lentivirus-mediated shRNA targeting Atg5, an essential protein for phagophore elongation, to suppress autophagy." (PMID 32462028, 2020). "Nevertheless, since the conditional deletion of Atg5 occurs very early during development, autophagy's role in the later stage of lupus progression remains uncertain." (PMID 32462028, 2020).
systemic lupus erythematosus (continued). "Several genome wide association studies (GWASs) have identified single nucleotide polymorphisms (SNPs) in ATG5 that seem to predispose for the autoimmune disease systemic lupus erythematosus (SLE) and lead to increased ATG5 levels in SLE patients." (PMID 31450711, 2019). "And elevated ATG5 expression level was observed in the splenic and renal macrophages of lupus mice and in peripheral blood mononuclear cells (PBMC) of SLE patients." (PMID 26509176, 2015). "Moreover, polymorphisms in IRGM have been linked to the multifactorial autoimmune disease systemic lupus erythematosus (SLE), as have polymorphisms in Atg5 and Atg7." (PMID 23577011, 2013). "In addition, genome-wide association studies showed that ATG5 is associated with systemic lupus erythematosus (SLE) in Chinese individuals, indicating that autophagy may be related to the pathogenesis of SLE." (PMID 34660181, 2021). "In a Tlr7 transgenic mice model of lupus induced by overexpression of Toll-like receptor 7, secretion of autoantibodies is reduced when autophagy is suppressed through knockout of the autophagy protein ATG5 in B cells." (PMID 33187196, 2020). "A more recent study observed that the administration of shATG5-lentivirus ameliorated proteinuria and decreased the level of serum anti-dsDNA antibody in lupus-prone mice, suggesting promising therapeutic innovations targeting ATG5; however, more investigation is needed to evaluate its side effects." (PMID 30386331, 2018). "It has been shown that knockout of Atg5 in B cells attenuates the development of autoantibody production, lymphocyte infiltration and mortality in toll-like receptor 7-transgenic mice, supporting an important role for B cell autophagy in the development of lupus-like autoimmunity." (PMID 34335611, 2021). "The ATG5/PRDM1 region has been linked to susceptibility of several autoimmune diseases, including RA and systemic lupus erythematosus (SLE)." (PMID 34101054, 2021). "In this regard, polymorphisms on ATG5, ATG10 and ATG16L1 have been associated with Paget’s disease of the bone, and SNPs in ATG5 and ATG7 have been extensively studied in the context of systemic lupus erythematosus." (PMID 33147747, 2020).